GZMB (granzyme B)
Diseases named in the same sentence as GZMB in open-access papers (continued):
Sharing a sentence is not in itself a finding about the gene and the disease.
tumor (continued). "Because immunity-based tumor elimination depends primarily on the activated CD8+ T cell, which exerts cytolytic capacity by secreting granzyme B (GZMB), we investigated the infiltrated CD8+ T cell abundance and activity in the tumor regions of ABZ-treated mice." (PMID 35577504, 2022). "Moreover, within the tumor region, they had a lower density of total CD4+ cells and a lower CD4 + FoxP3+/CD8 + Granzyme B+ cell ratio." (PMID 33947438, 2021). "Both subsets of CD8+ T cells from tumor samples expressed higher effector genes than nonmalignant samples, including chemokines (e.g., CCL5), cytotoxicity-associated genes (PRF1, GZMA, GZMB, GZMH), and proinflammatory cytokines (e.g., IL-32)." (PMID 34921160, 2021). "MUC16ecto- BiTEDs cocultured with T-cells in the absence of tumor cells did not display increased granzyme B, IL-2 or IFN-γ." (PMID 33936101, 2021). "Similarly, FATS deletion increased the expression of Granzyme B and IFN-γ in B16 tumor-infiltrating CD8+ T cells, which indicated the positive role of FATS deficiency in CTL activation." (PMID 34262035, 2021). "In particular, the expression of Granzyme B and perforin in Tregs could induce the death of NK and CD8+ T cells and suppress tumor clearance in vivo." (PMID 34576115, 2021). "In support of the cell signature analysis, IHC for CD8+ T cells and Granzyme B demonstrated CD8+ T cell infiltration of primary tumours, but that exhaustion had already taken place (i.e., an absence of Granzyme B+ cells)." (PMID 34290237, 2021). "Recently, new granzyme B targeting tracers have been developed whose tumour retention is dependent on granzyme B proteolytic activity as opposed to the current aldehyde tracer which quantifies the amount of biochemically active GZMB molecules at the tumour." (PMID 35936114, 2021). "The results showed that mice bearing B16-F10 tumors treated with combined regimen had longer survival than other groups (, and tumor samples of mice treated with PD-1 antibody or combined therapy had significantly higher levels of CD3, CD8, and granzyme B than IgG group." (PMID 34051805, 2021). "These anti-MUC1-CAR4 T cells showed anti-cancer activity against MUC1-expressing CCA cells by increased production of anti-tumor cytokines (TNF-α and IFN-γ), pro-apoptotic protein (granzyme B), and induction of CCA cell lysis both in 2D and 3D (spheroid) co-cultures." (PMID 33737613, 2021). "Whole-tissue tile scans of the CD19, CAR RNA FISH co-staining with either GZMB RNA FISH (n = 5) or IFNγ RNA FISH (n = 5) also indicated that the highest expression of GZMB but not IFNγ is in close proximity to the tumor." (PMID 34155235, 2021). "Circulating NK cells, unlike the tumour-associated NK cells, appeared to retain their cytolytic activity with most sub-populations expressing CD56dim, CD57, GzmB and CD16." (PMID 33917832, 2021). "Furthermore, considering the immunosuppressive nature of the tumor microenvironment, we expected to see greater differences between Met and ULN, with reduced GzmB and perforin in the Met situation." (PMID 34187852, 2021). "So far, various endogenous pro-apoptotic molecules such as granzyme B (GrB), truncated Bid (tBid), caspase-3, caspase-6 and apoptosis-inducing factor (AIF) have been utilized to induce apoptosis in tumor cells." (PMID 34488747, 2021). "In addition, we observed enhancement of not only CD8+ T cell infiltration but also DC infiltration and upregulation of CXCL9, CXCL10, GZMA, GZMB, and IFN-γ in Col6a1−/− tumor tissues compared with WT MCA205 tumor tissues." (PMID 34782761, 2021). "Furthermore, PRGN-2009–treated mice had greater numbers of multifunctional (IFN-γ+GzmB+) and other subsets of CD8+ T cells infiltrating the tumor compared with control." (PMID 33651712, 2021). "Tumor cells were all immunoreactive for CD3, granzyme B, and TIA-1; variable for CD56 (69.2%)." (PMID 34072328, 2021).
tumor (continued). "Tumor infiltrating lymphocytes with expression of these checkpoint inhibitors had higher expression of activation markers, but similar or lower levels of granzyme B expression compared to tumor infiltrating lymphocytes not expressing these checkpoints." (PMID 33981303, 2021). "Notably, the combination treatment with mifepristone and dual ICB further augmented the abundance of tumor-infiltrating CD8+ T cells and granzyme B+ CTLs, compared with mifepristone treatment alone." (PMID 34873175, 2021). "Paclitaxel, cisplatin, and doxorubicin treatment rendered tumor cells more sensitive to CTL killing by upregulating mannose-6-phosphate receptors (M6PR) on the tumor cell surface, which augments cell membrane permeability to granzyme B." (PMID 34497771, 2021). "The overall outcome may result in enhanced suppression by DKO TIL Treg cells, as reflected by reduced GzmB+CD8+ Teff, partially explaining the increased tumor growth in DKO mice compared to WT mice." (PMID 34798898, 2021). "Besides, the densities of Ki67+ CD8+, Granzyme-B+ CD8+, and CD107a+ CD8+ T cells were markedly upregulated in the combination therapy group, indicating the higher tumor-killing capability." (PMID 34526097, 2021). "Overall, a 2.5 to 5-fold increase in the granzyme B+ CD8+ T cell to Treg ratio in αCD40 and HT40-treated tumors compared to the untreated control was noted, which reflects enhanced mobilization of cytotoxic cells in the treated tumor." (PMID 33391491, 2021). "Besides, they can kill DCs within TDLNs and TME in a contact-dependent way where Tregs recognize tumor-specific antigens presented by class 2 MHC ligand on DCs and release granzyme B/perforin granules to eliminate them." (PMID 33868318, 2021). "Some level of tumor microenvironment characterization can often be achieved by genome and transcriptome-based technologies (including granzyme b/IFNg), flow cytometry and simple tumor cell killing assays but these are not cell specific." (PMID 33922052, 2021). "The increased expression of cytotoxic effector molecules GZMA, GZMB, GZMH, GZMM, GNLY, NKG7, and PRF178 but also of the thioredoxin function inhibitor TXNIP79, demonstrates a potent effector capacity to eliminate malignant cells and suppress tumor growth." (PMID 33602930, 2021). "Thus, via disruption of integrin-dependent adhesion, GZMB has been shown to inhibit tumor cell spreading, migration, and invasion on ECM, thereby potentially inhibiting tumor growth and invasion." (PMID 34972191, 2021). "To further investigate the side effects of the novel mAbs with respect to those of ipilimumab and atezolizumab, we also evaluated the levels of Granzyme B, usually released by either cytotoxic CD8+ T cells or by natural killer (NK) cells to eliminate tumor cells." (PMID 35008285, 2021). "Pre-clinical models have shown that the tubulin-targeting drug, paclitaxel, increases tumor cell permeability to granzyme-B (released from CTLs) and upregulates major histocompatibility complex (MHC) class I expression on cancer cell lines to induce tumor cell immunogenicity." (PMID 34135901, 2021). "This is concordant with the reduced level of BANK1 observed after B cell activation and in differentiated cells, as tumor B cells (GSE 22529) or plasma cells (GSE 6691), since Breg cells have also been shown to be highly differentiated cells and GZMB+ Bregs are enriched in plasmablast population." (PMID 33815360, 2021). "Therefore, our results indicated that CAR‐T cells induced apoptosis in haematologic tumour cells through IFN‐γ/STAT1 pathway and granzyme B/ perforin/caspase cascades." (PMID 33225580, 2021). "For example, granzyme B could release VEGF and TGF-β by cleaving a number of glycoproteins, their anchors to ECM, thereby promoting vascular permeability and tumor angiogenesis during chronic inflammation." (PMID 33868318, 2021).
tumor (continued). "Based on the constitutively high expression of major cytolytic enzymes, such as perforin and GZMB, in TRM-like cells, the persistence of TRM cell state in a tumor may be a major determinant of the effective killing of cancer cells." (PMID 34663810, 2021). "For CD8+ T cells, although the cytotoxic molecules (GZMA, GZMB, NKG7, and PRF1) were highly expressed, a fraction of CD8+ T cells showed positive with exhaustion biomarkers (CTLA4, PDCD‐1, and TIGIT), indicating their tumor‐cytotoxic activity was constrained." (PMID 34185421, 2021). "Tumoural infiltration of CD8+ T cells and granzyme B production were increased by nintedanib, and its antitumour activity was attenuated by antibody-mediated depletion of these cells, indicating that nintedanib suppressed tumour growth in a CD8+ T cell-dependent manner." (PMID 33299131, 2021). "In addition, the cytotoxic effector CD4+ T cells, most closely related to Th1 subset, can directly eliminate tumor cells through the MHC class II-dependent manner, which destroy target cells by secreting granzyme B and perforin." (PMID 33791306, 2021). "“Hot tumours” describe those where the cytotoxic lymphocytes (CTLs) are infiltrated and inflamed, showing high expression of activation marks such as PD1 and PDL1, with increased IFNγ and granzyme B, and a low stromal component (CMS1 subtype)." (PMID 33669775, 2021). "Furthermore, granzyme B secretion by CD4+ and CD8+ T cells were higher in the tumor lesions of mice treated with compound 968 with anti-PD-L1 antibody compared with the other treatment groups." (PMID 34944392, 2021). "Furthermore, injection of PEGylated IL-10 into MMTV/HER2 transgenic mice led to tumor rejection that was dependent on activated CD8 T cells in an IFN-γ and Granzyme B-dependent manner." (PMID 34769278, 2021). "Tumor regions were found to have an increased infiltration of regulatory T cells (Tregs) by 87% and a reduced infiltration of CD8+ T cells, which also showed a lower expression of granzyme A (GrA), granzyme B (GrB), and perforin." (PMID 34830949, 2021). "Other chemokines that could draw Tregs into tumor lesions, such as the ligands for CCR4 and CCR10, are also largely produced in TME, whereas their contribution to granzyme B expression in Tregs is yet to be established." (PMID 33868318, 2021). "In local tumor tissues, EA obviously increased NK cell proportion and slightly improved CD8+ T cell proportion and noticeably increased the expression of perforin protein and granzyme B protein." (PMID 35095910, 2021). "Using the Hyperion imaging system we validated higher lymphocyte infiltration with osimertinib treatment and also observed a shift of proliferative activity (Ki67) from tumor cells to CD3+ cells and cytolytic activity as measured by co-staining of CD8 and Granzyme B under treatment." (PMID 34535668, 2021). "For example, Zhang et al36 indicated that GzmB, which is released from natural‐killer (NK) and CD8+ T lymphocytes, can directly cleave GSDME and consequently enhance the anti‐tumour immunity by activating GSDME‐mediated pyroptosis in breast cancer cells and melanoma." (PMID 34590363, 2021). "Even when encountered with OX40 agonist, potential immunotherapy that enhances anti-tumor immune responses, it did not harm the regulatory ability of Tregs due to the simultaneous increase in granzyme B, IFN-γ, and T-bet expression." (PMID 33868318, 2021). "In the tumours treated with DPX-R9F/CPA/anti-PD-1 the levels of gzmB and ifng transcripts were slightly elevated but not statistically different from the levels in the untreated control group." (PMID 33627686, 2021). "Here we found that intratumor CD8+ T cells isolated from SmoΔM tumor-bearing mice produced significantly higher IFN-γ and GzmB (P < 0.005) when compared with Smofl/fl, suggesting that Hh-induced M2-polarized TAMs could suppress intratumor CD8+ T cell function." (PMID 33749663, 2021).
tumor (continued). "Interestingly, ICB treatment of mice bearing the YUMM1.7 tumors, resulted in marked increases in tumor infiltrating CD8 lymphocytes and granzyme B expression, nearing the baseline observed in YUMM1.7-CM generated tumors." (PMID 34295826, 2021). "After 1 month, this inflammatory infiltrate is inverted, with a low level of mononuclear infiltration and a greater number of granzyme-B+ lymphocytes, suggesting that ECT helps with the long-term local tumor control by inducing persistent immune response of T-cytotoxic lymphocytes." (PMID 34947852, 2021). "The PDO TILs activities were evaluated by treatment with anti-PD-1 or anti-PD-L1 in murine tumor organoids that showed a strong increase of CD8 TILs and T cell activation markers such as interferon-gamma (IFNγ), perforin-1 (PRF1), and granzyme B recapitulating the PD-1/PD-L1 immune checkpoint." (PMID 34074330, 2021). "At 9 days post‐adoptive transfer both tumour and draining lymph node Lck‐Cre;Ptpn2fl/fl OT‐1 T cells were more active, as assessed by the PMA/ionomycin‐induced expression of effector molecules, including IFNγ, TNF and granzyme B." (PMID 31803974, 2020). "Additionally, the DP T cell subset in the tumour, which comprised primarily of TEM and CD69-expressing cells, contained cells with high levels of granzyme B, suggesting that TRM-like DP T cells also have cytotoxic properties." (PMID 32439888, 2020). "We also cultured mouse and human Teff cells in conditioned medium and assessed the expression of effector molecules, including granzyme B, tumour necrosis factor alpha (TNF-α) and interferon gamma (IFN-γ), all of which are important in mediating the tumour-cell-killing activity of Teff cells." (PMID 32694789, 2020). "Specifically, the tumor cell apoptosis from Eu-FBCP/PTX treatment triggered the expression of HMGB1 and CRT, demonstrating greater DC maturation and activation of antitumor IFN-γ+CD8+ and granzyme B+CD8+ T cells compared with Eu-s/PTX." (PMID 34138119, 2020). "In addition, the activated OT1-iT cells secreted comparable levels of IFNγ and GzmB to OT1-T cells, indexing their tumor-eradicating behavior." (PMID 32669292, 2020). "Actually, Tα1 promoted the infiltration of CD8+ T cells penetrating the viable and nonviable tumor tissue, a positive prognostic factor for the efficacy of ICI, and increased the expression of CD8 associated markers (GzmB and Perforin)." (PMID 32817121, 2020). "Furthermore, we detected an increased frequency of CD4+ T cells producing granzyme B indicating their cytotoxic activity (CTL), possibly as a result of chronic exposure to the tumor." (PMID 32370785, 2020). "Peripheral Vδ1 T cells and Vγ9Vδ2 T cells could recognize tumor cells through TCRγδ and NKR, and kill them through perforin-granzyme B, Fas/FasL and TRAIL." (PMID 33664732, 2020). "We present here that Granzyme B expressing CD8αβ T cells increase in the tumor after Treg depletion, while no other cell subset displays increased cytotoxic activity." (PMID 32185408, 2020). "These variations, including those in GZMB, CXCL11, and NEIL3 suggest that the differences between patients from both races could be related to their immune response at the tumor niche." (PMID 32983990, 2020). "CD8+ tumor infiltrating lymphocytes (TIL) in EC show defective granzyme B and perforin expression, leading to a lack of tumor-induced suppression activity." (PMID 32226771, 2020). "Notably, the mice that expressed highest levels of Granzyme B+ and PD-1 CD8+ T cells demonstrated superior tumor regression (especially in CFUS group)." (PMID 32206098, 2020). "In addition, NK cells induce the expression of FasL/Fas (FAS/FASLG), leading to apoptosis of tumor cells, and also affect tumor cells via multiple approaches, including direct lysis by perforin 1 (PRF1) and granzyme A and B (GZMA and GZMB)." (PMID 33276627, 2020).
tumor (continued). "The increased expression of Granzyme B post reovirus treatment in a patient biopsy sample (documented by immunohistochemistry) also demonstrates activation of CD8+ T cells, and highlights reovirus-directed tumor cell-specific destruction." (PMID 32552875, 2020). "We speculate that RNF183, which is highly expressed in the tumor microenvironment, leads to a better prognosis of UCEC by regulating the expression of inhibitory immune checkpoint proteins PD-1, LAG3 and GZMB on exhausted T cells." (PMID 33324448, 2020). "Moreover, the activated tumor-infiltrating CD8+ T cell population and granzyme B expression were increased in the mice treated with the ODN1585 and anti-PD-1 antibody combination, indicating that this combination treatment improved immune activity in the mice." (PMID 32483468, 2020). "Granzyme B and Fas were elevated in both G-CSFR−/− CD4+ and CD8+ treated tumors, suggesting that G-CSF plays a role in both T helper and cytotoxic T cell activity in the tumor microenvironment." (PMID 33042110, 2020). "Antagonizing ZAP-70 inhibition by siRNA against Rasal1 increased the number of CD8+ tumor-infiltrating T-cells expressing granzyme B and interferon gamma (no ‘1') and enhanced tumor killing." (PMID 33194762, 2020). "Enhanced numbers of GzmB producing CD4+ and CD8+ T cells in tumor patients after combination treatment with antibodies against PD-1 and CTLA-4 have previously been described, but this study did not perform a detailed characterization of the GzmB producing cells." (PMID 32226027, 2020). "Tumor-derived exosomes were shown to mediate the conversion of CD4+ CD25− T cells into CD4+ CD25high FOXP3+ regulatory T cells with enhanced expression of Fas ligand, IL-10, TGF-β1, CTLA-4, granzyme B, and perforin." (PMID 32499786, 2020). "Additionally, it was found that the lysate of L. acidophilus promoted the anti-tumor effects of CTLA-4 by reducing the quantity of Treg as well as M2 cells, while increasing the levels of T cells and IFN-γ, Granzyme B, and TNF-α." (PMID 33318319, 2020). "Importantly, tumor-infiltrating CD8+ T cells in SMF-treated mice produced more antitumor granules and cytokines, including granzyme B, IFNγ and TNFα, than their counterparts from control mice." (PMID 32884074, 2020). "As for T cell related cytotoxins, essential in tumor killing, stacked FPKM of 8 genes (PRF1, GZMM, GZMK, GZMH, GZMB, GZMA, FASLG, and FAS) demonstrated that these genes were more highly expressed 1.7-fold (P = 0.037) in IFNγ positive tumors compared to IFNγ negative tumors." (PMID 32265897, 2020). "Thus, hetIL-15 treatment led to a significant accumulation of GzmB+ CD8+, CD4+ T and NK cells per tumor." (PMID 32461349, 2020). "As expected, compared to that of GL-261 WT tumor-bearing mouse CD8 + T cells, the antitumor immunity of GL-261 LGALS9−/− tumor-bearing mouse CD8 + T cells was enhanced, with an increased proportion of Ki67-positive cells and enhanced expression of IFN-γ/GzmB." (PMID 33093453, 2020). "Moreover, it increased the frequency of CD8+ T-cells, and mRNA levels of granzyme B and IFN-γ in the tumor." (PMID 32499785, 2020). "In addition, IFN-DCs exhibit cytotoxic activity against various tumor cell lines, express a wide range of cytotoxic ligands (TNFα, TRAIL, FasL, perforin), and also secrete granzyme B, which is barely produced by IL-4-DCs." (PMID 32326230, 2020). "CEA-TCB-treated tumors displayed a clear upregulation of several pro-inflammatory cytokines and chemokines [MIPα (CCL3), CXCL10, CXCL13, CXCL9, IL-16, and I-TAC (CXCL11)], an increase in intra-tumor CD3+, CD4+, CD8+ T-cells that express high levels of 4-1BB, PD-1, and upregulation of GZMB." (PMID 33330050, 2020). "In contrast, after activation for 12 h, the percentage of granzyme B+ NKG2A− CD8+ T cells from the tumor and normal tissue had a tendency to decrease, but not NKG2A+ CD8+ T cells." (PMID 32010126, 2019).